KRAS (KRas proto-oncogene, GTPase)
Diseases named in the same sentence as KRAS in open-access papers (continued):
Sharing a sentence is not in itself a finding about the gene and the disease.
adenocarcinoma (674 papers, 1989 to 2026). A common cancer characterized by the presence of malignant glandular cells. "Mutations in KRAS, particularly at codon 12, are frequent in adenocarcinomas of the colon, lungs and pancreas, driving carcinogenesis by altering cell signalling and reprogramming metabolism." (PMID 41266617, 2026). "KRAS mutations are relatively common in gastric-type adenocarcinomas and mesonephric carcinomas, making KRAS-targeted therapy a subject of interest." (PMID 41155343, 2025). "Similar to human adenocarcinoma, the cell lines we used here also harbor the KRAS mutation, a mutation that can potentially impact the expression or function of CD26." (PMID 41426321, 2025). "All three patients with SD had NSCLC, two of whom had low PD-L1 expression (1-49%), STK11 wildtype but KRAS-mutated adenocarcinoma, and were previously treated with an immune checkpoint inhibitor." (PMID 41523436, 2025). "KRAS mutations represent the single most common driver in NSCLC (occurring in ~30% of adenocarcinomas, with the KRAS G12C variant comprising about 13% of cases)." (PMID 40723270, 2025). "IHC staining and targeted exome sequencing confirmed that the histological subtype (adenocarcinoma) and the genotype (KRAS G12C mutation) were maintained in the xenograft and the PDX." (PMID 40723176, 2025). "The first patient was male with left-sided CRC adenocarcinoma and synchronous liver metastases and harbored KRAS c.35G>T (p.Gly12Val) and NRAS c.181C>A (p.Gln61Lys) mutations." (PMID 40075837, 2025). "The second LUL nodule showed well-differentiated adenocarcinoma with predominant acinar pattern stage IA2 (cT1bN0M0) with KRAS mutation." (PMID 40642683, 2025). "KRAS mutations are usually associated with the female sex, adenocarcinoma, and smoking; therefore, patients with these clinical features are overrepresented compared to the average NSCLC stage III population." (PMID 39941616, 2025). "Approximately 25% of the patients with adenocarcinoma in a North American population have KRAS mutations." (PMID 41153394, 2025). "The majority of patients with NSCLC had adenocarcinoma (n = 4) and Kirsten rat sarcoma (KRAS) gene mutation (n = 4)." (PMID 41523436, 2025). "In KRAS-mutant adenocarcinoma, high IL-1β expression was associated with modestly longer TOT on immunotherapy (7.4 vs. 6.4 months; HR 1.15; p = 0.041), but not OS." (PMID 40940992, 2025). "A549 represents a well-validated adenocarcinoma model harboring characteristic KRAS mutations and, critically, exhibits dysregulated iron metabolism-a pathophysiological feature essential for DHA bioactivation that mirrors clinical NSCLC profiles." (PMID 40697663, 2025). "KRAS mutations are considered a central part of the pathogenesis of adenocarcinomas of many organs including lungs, colorectal, and pancreas." (PMID 40860802, 2025). "For adenocarcinomas, KRAS mutations led to a higher enrichment of genus Bacteroides, Ruminococcus, and Peptostreptococcus, while genus Geobacter and Skermanella were less enriched compared to their wild‐type counterparts." (PMID 40485603, 2025). "In contrast, the KRAS G12C mutation rate (13.3%) was in line with published data, which report G12C in approximately 12–14% of adenocarcinomas, confirming its relevance as a common actionable alteration in smoking-related NSCLC." (PMID 40867330, 2025). "CL7 included only combined adenocarcinomas, most of which harbored mutations in KRAS and/or KEAP1 and STK11." (PMID 40144596, 2025). "STK11 alterations in KRAS-driven NSCLC adenocarcinomas are associated with low PD-L1 (Programmed Death-Ligand 1) levels, leading to reduced efficacy of anti-PD-1 monoclonal antibody therapy." (PMID 39011112, 2024).
adenocarcinoma (continued). "In summary, we found that males and current smokers, as well as tumors with non‐adenocarcinoma histology, KRAS mutations, and tissue samples from distant nodes, were associated with high PD‐L1 expression." (PMID 38456253, 2024). "In mucinous adenocarcinoma, which account for about 5% of adenocarcinomas, until recently, only KRAS mutations were known to be enriched, detected in 50–80% of cases." (PMID 38347643, 2024). "Recent studies have highlighted the substantial impact of STK11 mutations in the highly prevalent KRAS-driven NSCLC adenocarcinomas, presenting distinct biological characteristics, therapeutic susceptibilities, and immune profiles." (PMID 39011112, 2024). "Molecularly, G12V, and G12D are the most common KRAS mutations in mesonephric-like adenocarcinoma, and concurrent ARID1A and PIK3CA mutations are relatively common, with 1q copy number gain being the most common." (PMID 38444000, 2024). "In our sample group, we identified only one patient with an EGFR mutation and one with a KRAS mutation (both patients have adenocarcinoma)." (PMID 38893104, 2024). "Individuals with advance-staged of adenocarcinoma and KRAS mutations, detected by next-generation sequencing, having undergone at least one line of therapy were included for analysis." (PMID 37490263, 2024). "Of the IA patients, KRAS mutations were most frequent in acinar-predominant (5.63%), followed by solid-predominant adenocarcinoma (4.76%), lepidic-predominant (2.70%), and papillary-predominant carcinoma (0.00%)." (PMID 39364008, 2024). "The most frequent BRAF mutation is the V600E constitutively activating point mutation found in 2–4% of adenocarcinomas, which is mutually exclusive with KRAS mutations." (PMID 39513892, 2024). "A549 cells are adenocarcinoma cells that harbor KRAS G12S mutation but wildtype EGFR, whereas H1975 harbors EGFR mutations L858R and T790M." (PMID 39201772, 2024). "This cell line is mutated for KRAS, and for this molecular type of adenocarcinomas, only the ones expressing high levels of PDL1 are good responders to ICI therapy." (PMID 38391918, 2024). "Inhibition of the RAS/MAPK pathway can also be a therapeutic modality when the mesonephric-like adenocarcinoma is combined with KRAS/NRAS mutations." (PMID 38444000, 2024). "KRAS mutations in lung cancer are found predominantly in adenocarcinoma, representing 37% of cases, while roughly 4% of squamous cell carcinomas harbour these alterations." (PMID 38347643, 2024). "In a study of 210 CRC patients, investigators found that the KRAS mutation was associated with female gender, left localization, classical adenocarcinoma, vascular invasion, and the presence of positive lymph nodes and advanced disease stage in MSS cases." (PMID 39125664, 2024). "The histological subtype was largely Lieberkuhnian adenocarcinoma (95%), and KRAS, NRAS and BRAF genes were mutated in 58%, 4% and 8% of cases, respectively." (PMID 39796718, 2024). "Most prevalent actionable mutations in adenocarcinoma include KRAS, EGFR, ALK, RET, ROS1, BRAF, HER2, MET." (PMID 37301854, 2023). "EBVaGCs with intestinal histology were frequently accompanied by genetic alterations, which were known to frequently occur in conventional intestinal-type adenocarcinoma, including KRAS, FBXW7, MUC6, ERBB2, CTNNB1, and ERBB2 amplification mutations." (PMID 37945587, 2023). "Of the 7 invasive adenocarcinomas with KRAS mutations, 6 were of the acinar‐like growth type and 1 was of the adherent growth type." (PMID 37340599, 2023).
adenocarcinoma (continued). "When subdividing by CUP histological type, the adenocarcinoma was the most frequently mutated (10/12 samples); in addition, only adenocarcinomas harbored KRAS mutations." (PMID 36346458, 2023). "One of the most common genetic changes characteristic of the adenocarcinoma lung cancer subtype is the KRAS gene mutation affecting the proliferation and development of chemo-resistance and cancer cell survival." (PMID 36830984, 2023). "KRAS gene mutations prevail in patients with adenocarcinoma, in the course of which metastases to the CNS are frequent (40–60% of patients)." (PMID 37509393, 2023). "KRAS mutations are found in 30% of NSCLC adenocarcinomas, while patients with KRAS mutations are KRAS/STK11 co-mutated 15–32% of the time in the metastatic setting." (PMID 37373999, 2023). "This study also showed a higher prevalence of 51% of KRAS variants in NSCLC adenocarcinoma patients, in contrast to previously reported prevalence of 20–40%." (PMID 35723337, 2022). "A single KRAS mutation was identified in a patient with an adenocarcinoma; this missense mutation resulted in KRAS gain of function." (PMID 35267442, 2022). "Patients who were KRAS-mutant, and having a non-adenocarcinoma histology, as well as those with fusion mutation were significantly associated positive PD-L1 and strong PD-L1 expression." (PMID 35980949, 2022). "Surprisingly, in this series 92% of cases were adenocarcinoma and KRAS mutation and ROS1 rearrangement was reported in 7 cases and 1 case, respectively." (PMID 35842660, 2022). "The mutations identified in patients affected by adenocarcinoma were: mutation of KRAS in 12 patients (exon 2, codon 11 in 12 and exon 3, codon 61 in 1)." (PMID 36714142, 2022). "The 2 CoADC had >70% of adenocarcinoma component and harboured a KRAS mutation in one case and an ALK-EML4 fusion gene in the other." (PMID 36230576, 2022). "The incidence of KRAS mutation in adenocarcinoma among the Asian population is approximately 10–15%." (PMID 35524294, 2022). "KRAS mutations have been linked to adenocarcinoma histology, positive smoking history, and Caucasian ethnicity, although differences have been described across KRAS mutational variants subtypes." (PMID 36358848, 2022). "In NSCLC adenocarcinoma, KRAS G12C, G12V, and G12D are the most common KRAS alterations observed, seen in 40.5%, 19.8%, and 14.7% of KRAS mutated adenocarcinoma, respectively, where these 3 variants account for over 75% of cases." (PMID 36136862, 2022). "KRAS mutations represented 50% (2/4) of all mutations in the Inuit adenocarcinoma samples, compared to 53.6% (192/358) of cBioPortal adenocarcinoma mutations." (PMID 35621648, 2022). "The high prevalence of KRAS mutation in our patients with adenocarcinoma (30.7%) is comparable to what is reported in the literature for Caucasian patients." (PMID 36714142, 2022). "A similar effect was observed in the KRAS-mutated adenocarcinoma cell line model (A549-FL), used to examine the metastasis mechanisms that identified epithelial–mesenchymal transition (EMT) markers." (PMID 35887120, 2022). "Our results support the extension of molecular profiling in the diagnostic routine, especially for LCNECs combined with an adenocarcinoma component to evaluate the presence of druggable KRAS G12C mutations and fusion genes." (PMID 36230576, 2022). "For example, epidermal growth factor receptor (EGFR) mutations are more frequently found in female patients who are never smokers and who have adenocarcinoma histology, whereas KRAS mutations are more common in adenocarcinoma patients who are smokers." (PMID 33707471, 2021). "In KRAS-mutated colorectal and lung adenocarcinoma cells, PI3K/AKT pathway activation is dependent on RTK–WT RAS signaling (see Section 3.3), and thus inhibition of RTK signaling should indirectly inhibit PI3K activation." (PMID 33924994, 2021).
adenocarcinoma (continued). "Regarding lung LCNEC, the adenocarcinoma-like subtype defined by the presence of KRAS or STK11 mutations have higher response rates to the pemetrexed/platinum chemotherapy doublet." (PMID 33562726, 2021). "Recent molecular studies have demonstrated KRAS mutations in most mesonephric adenocarcinomas of the cervix, whereas a smaller number show activating NRAS mutations." (PMID 33570865, 2021). "Despite miR-34 expression being associated with survival in KRAS-mutated adenocarcinoma patients, little is known on the molecular mechanisms by which miR-34c-3p and KRAS interact." (PMID 32948832, 2021). "All these effectors have been extensively investigated to find new therapeutic strategies for KRAS-mutated adenocarcinoma." (PMID 32948832, 2021). "Kirsten rat sarcoma (KRAS) mutations are present in up to 30% of NSCLC (especially in adenocarcinoma histotype) and have been identified decades ago." (PMID 35004317, 2021). "Most KRAS mutations patients are males (60%), current or former smokers (63% and 33%, respectively) with adenocarcinoma (80%)." (PMID 34918209, 2021). "Approximately 29% of NSCLC patients have KRAS gene mutations, among whom those with adenocarcinoma and a history of smoking are the most commonly diagnosed." (PMID 34217313, 2021). "Briefly, in the adenocarcinoma subtype, 26.2% (n = 195 out of 744) were KRAS-mutated, with p.Gly12Cys being the most frequent mutation identified in 9.4% (n = 70 out of 744), followed by p.Gly12Val in 6.2% (n = 46 out of 744)." (PMID 33956502, 2021). "In the majority of cases KRAS codon 12 mutated tumors were associated with female gender (P = 0.01), classical adenocarcinoma (P = 0.02), advanced TNM stage (P = 0.04) and presence of positive lymph node (P = 0.004)." (PMID 33784337, 2021). "Lung cancer, the most common cancer worldwide, is a promising use case for these new therapies, as adenocarcinomas in particular frequently harbor KRAS mutations." (PMID 34976827, 2021). "Conversely, in KRAS-mutated colorectal and lung adenocarcinoma cells, PI3K/AKT pathway activation is dependent on RTK signaling." (PMID 33924994, 2021). "In the same way, some studies have shown that KRAS mutations tended to occur more frequently in classical adenocarcinoma tumors as reported in our study." (PMID 33784337, 2021). "Analysis for these gain-of-function mutations in KRAS showed concomitant KRAS mutations with loss of STK11 in adenocarcinoma." (PMID 33652656, 2021). "KRAS G12A somatic point mutation in adenocarcinomas is categorized clinically as ineligibility criteria for anti-epidermal growth factor receptor (EGFR) monoclonal antibody therapies." (PMID 33652552, 2021). "In the present work, we demonstrate that the chimaera reduces expression of CDK1 protein, opening a new possible therapeutic scenario for KRAS-mutated adenocarcinoma." (PMID 32948832, 2021). "Within NSCLC, KRAS mutations are almost exclusively seen in adenocarcinomas, with up to 40% of adenocarcinoma harboring oncogenic mutations of the KRAS gene." (PMID 34573384, 2021). "The importance of molecular targeting (identifying presence of mutations) cannot be understated as there is evidence for mutual exclusiveness between EGFR-activating mutations and KRAS mutations that are often seen in adenocarcinoma." (PMID 34439273, 2021). "The KRAS mutation rate was 69.2% versus 35.3% in the mucinous and adenocarcinoma NOS MSS cohorts, respectively (p = 0.03)." (PMID 32984045, 2020). "In western countries, the most frequent driver mutation in adenocarcinoma is found in the Kirsten rat sarcoma viral oncogene homolog (KRAS)." (PMID 33272262, 2020). "Multiregional analysis of an adenocarcinoma harboring two IDH2 mutations revealed parallel evolution originating from a KRAS‐mutated lineage, further supporting subclonal evolution promoted by IDH1/2 mutations." (PMID 32333643, 2020).
adenocarcinoma (continued). "KRAS mutations were found in 100% of the mucinous hypermutator patients compared to just 16.7% of adenocarcinoma NOS hypermutator patients (p = 0.11)." (PMID 32984045, 2020). "When only the adenocarcinoma cases were examined, KRAS exhibited the highest rate of mutation (35.55%)." (PMID 32756609, 2020). "In NSCLC patients, KRAS mutations are more common in young women diagnosed with adenocarcinoma who have a history of smoking." (PMID 33022831, 2020). "To date, the functional link between the integrin-dependent signaling and the NSCLC malignancy largely comes from the αvβ6 integrin dependence of KRAS mutated adenocarcinomas." (PMID 32793596, 2020). "These cells have wild type EGFR and KRAS mutation and are present in about 30% of adenocarcinoma 43-45." (PMID 32922539, 2020). "KRAS is commonly mutated in sporadic CRCs (35–45%) and is associated with poor prognosis; according to the adenocarcinoma sequence, KRAS mutations occur after APC mutations." (PMID 33374459, 2020). "Most patients in both the KRAS mutation and wildtype subgroups had adenocarcinoma and stage IV disease." (PMID 32607238, 2020). "It is also worth noting that when observing mutation frequencies among adenocarcinoma cases, which is the most frequently observed subtype, the results were lower than those observed in previous studies except the KRAS mutation, which was 10% higher." (PMID 32756609, 2020). "Their results revealed differences in mutation frequency between adenocarcinoma and SCC, and as was expected, the characteristic activating mutations of adenocarcinoma such as KRAS, HRAS, NRAS, and EGFR were identified only in 3% of SCCs." (PMID 32604993, 2020). "The current study aims to pursue synthetic lethal-type targeting of this pathway for NSCLC, particularly for the subset of adenocarcinomas exhibiting KRAS mutations." (PMID 32793596, 2020). "The G12/C codon change appears particularly enriched in these KRAS mutant NSCLC adenocarcinomas and promotes epithelial-mesenchymal transition (EMT)-linked disease progression." (PMID 32793596, 2020). "KRAS mutations have also been documented in mesonephric-like adenocarcinomas of the female genital tract." (PMID 31266530, 2019). "Nodule type was significantly different between the two mutations (P = 0.035), and all KRAS mutation adenocarcinomas were SN tumors." (PMID 31783917, 2019). "KRAS, ARID1A, ABL1, ATM, RET, and CDH1 mutations have been detected in the mesonephric adenocarcinomas containing sex cord-like pattern; among these genes, KRAS mutation was the most frequent." (PMID 31739799, 2019). "In NSCLC, KRAS-mutations mostly occur in codon 12 and are almost exclusively found in patients with adenocarcinomas." (PMID 31212989, 2019). "EGFR and KRAS mutations were more frequently observed in adenocarcinomas (10.2% vs. 0%, P = 0.042; 35.6% vs. 5.3%, P = 0.001 respectively)." (PMID 31668020, 2019). "Further studies are warranted to validate these in a larger patient cohort and identify further markers of interest such as ROS1 and RET rearrangements, other EGFR mutants and in NRAS-, KRAS-mutated adenocarcinomas." (PMID 30889898, 2019). "In contrast, oncogene-induced senescence is likely to reduce the frequency of the stepwise progression in KRAS- or BRAF-mutated adenocarcinoma." (PMID 29690599, 2018). "The clinicopathological characteristics of EGFR-mutated and KRAS-mutated adenosquamous cancers is comparable to those observed for their adenocarcinoma counterpart." (PMID 30060526, 2018). "KRAS mutations were seen in AAHs and paired adenocarcinomas, supporting a role for KRAS mutation as an early genetic event during lung tumorigenesis." (PMID 30060526, 2018).